BRAF (B-Raf proto-oncogene, serine/threonine kinase)
Diseases named in the same sentence as BRAF in open-access papers (continued):
Sharing a sentence is not in itself a finding about the gene and the disease.
ganglioneuroma (3 papers, 2022 to 2025). A benign neuroblastic tumor of the sympathetic nervous system that occurs in childhood. "We identified five female patients clinically suspected of having ROHHAD(-NET); among them in two patients a NET was found: a ganglioneuroma and a low grade cerebellar ganglion cell tumor with BRAF mutation." (PMID 40775360, 2025). "Importantly, these authors discovered that 20.0% (3/15) of the tumors studied by CP (PCC and ganglioneuroma) had BRAF mutations (K601E and K601N) and 46.7% (7/15) had HRAS mutations (Q61R, Q61L, G13R) based on genetic findings from the two cases studied by the NGS panel." (PMID 36187102, 2022).
glomus tumor (3 papers, 2024 to 2025). A rare benign or malignant mesenchymal neoplasm arising from cells that resemble the modified smooth muscle cells of the glomus body. "Approximately 6% of glomus tumors with uncertain malignant potential exhibit the BRAF V600E mutation, and the majority are positive for PDGFRB staining." (PMID 39776317, 2025). "The genetic basis of glomus tumors is yet to be fully elucidated; however, BRAF V600E mutations have been reported in approximately 6–11% of sporadic cases." (PMID 39392364, 2024). "A recent study revealed that BRAF V600E mutations may be associated with a malignant phenotype in glomus tumors; however, larger cohorts and multicenter studies are required to confirm these findings." (PMID 40255432, 2025). "Given the absence of standard systemic treatment in stage IV malignant glomus tumors, we considered including the patient in a phase I study with a BRAF inhibitor." (PMID 39392364, 2024). "BRAF V600E mutations were detected in six tumors (6%), all of which were classified as malignant glomus tumors or GT-UMP, suggesting that BRAF mutations could be associated with a more aggressive biology." (PMID 39392364, 2024).
Hydrocephalus (3 papers, 2022 to 2025). Hydrocephalus is an active distension of the ventricular system of the brain resulting from inadequate passage of CSF from its point of production within the cerebral ventricles to its point of absorption into the systemic circulation. "In detail, patient 5 presented with hydrocephalus at 17 months old and was diagnosed with a hypothalamo-chiasmatic PXA BRAF V600E mutation." (PMID 35328218, 2022).
hypopituitarism (3 papers, 2021 to 2022). A condition of diminution or cessation of secretion of one or more hormones from the anterior pituitary gland. "In conclusion, our murine models illustrate a role for BRAF and, more generally, the MAPK signalling pathway in pituitary development, and explain the underlying mechanism by which activating mutations in components of the MAPK pathway can lead to hypopituitarism." (PMID 33795686, 2021).
inflammatory bowel disease (3 papers, 2017 to 2025). A spectrum of small and large bowel inflammatory diseases of unknown etiology. "Our patient’s case illustrates this sporadic pattern well, as he had no family history of cancer, he tested negative for KRAS, NRAS, BRAF, and PIK3CA mutations, and he showed no signs of inflammatory bowel disease." (PMID 41487588, 2025).
intraepithelial neoplasia (3 papers, 2012 to 2023). A precancerous neoplastic process that affects the squamous, glandular, or transitional cell epithelium without evidence of invasion. "We found only 5 BRAF V600E mutations present in high grade intraepithelial neoplasia." (PMID 26910894, 2016). "Taken together, sessile serrated lesions with and without intraepithelial neoplasia were more often located in the right colon (72% right sided versus 26% left sided) and frequently showed BRAF mutations (72% BRAF mutation versus 6 % KRAS mutation)." (PMID 23045412, 2012). "Interestingly, in wild type BRAF and KRAS lesions with high grade intraepithelial neoplasia, moderate to strong c-MYC expression correlated with nuclear beta-catenin localization." (PMID 23045412, 2012).
iris melanoma (3 papers, 2019 to 2020). A uveal melanoma that arises from the iris. "As BRAF mutations do occur in iris melanoma, genetic testing to detect BRAF mutations can be considered." (PMID 32718045, 2020). "In contrast to posterior UM, mutations in BRAF (0–47%) and NRAS have been described in iris melanoma, although the frequency of their presence is unclear, and they might not represent driver mutations." (PMID 32718045, 2020). "As for targeted therapy, it is unknown whether BRAF-mutated iris melanoma responds to BRAF(/MEK) inhibition, as it is not described in the literature." (PMID 32718045, 2020).
liver cirrhosis (3 papers, 2021 to 2023). "The minimum width of rim fluorescence surrounding tumors is negatively associated with the tumor type, tumor size, liver cirrhosis, neoadjuvant chemotherapy, and KRAS and BRAF mutation (all P > 0.05)." (PMID 36484905, 2023). "Compared with the common homozygous genotype, the effect of the GC or GC + CC variant genotypes for COL1A1 rs2269336 and the TC or TC + CC genotypes for BRAF rs76603725 was more evident in males, liver cirrhosis, tumor number ≥3, tumor maximum diameter ≥5 cm, and tumor in two lobes." (PMID 34007838, 2021).
liver disease (3 papers, 2016 to 2026). "NGS confirmed BRAF V600E mutation (VAF 0.5%), supporting active liver disease at the time of transplantation, warranting resumption of vemurafenib post-transplant." (PMID 41170802, 2026). "Several authors suggest that BRAF status should be taken into consideration prior to liver surgery in patients with extensive liver disease." (PMID 34887523, 2022).
lung disease (3 papers, 2018 to 2022). "In particular, while BRAF was detected in all samples, Ki67 was significantly lower in benign and malignant lung diseases than in controls and NETs." (PMID 29467960, 2018). "Patients with BRAF mutation had significantly more right-sided and undifferentiated tumors, showed MSI status, had more infra and supradiaphragmatic adenopathy and peritoneal metastasis, and had less pulmonary disease, which is consistent with previous literature data." (PMID 31319569, 2019).
mast cell tumor (3 papers, 2015 to 2025). "Larger sample sizes with better annotation would strengthen the association between BRAF mutation and mast cell tumor infiltration in CRC primary patient samples." (PMID 41039118, 2025).
meningeal melanoma (3 papers, 2015 to 2025). "Furthermore, some additional molecular alterations, such as SF3B1, EIF1AX, and BAP1 mutations, confer a significant aggressive course in meningeal melanoma, while both primary diffuse leptomeningeal melanocytosis or melanomatosis are often NRAS mutated and rarely BRAF mutated." (PMID 39061148, 2024).
mesothelioma (3 papers, 2015 to 2022). A usually malignant and aggressive neoplasm of the mesothelium which is often associated with exposure to asbestos. "Based on the interquartile range, BRAF expression was widely distributed in COADREAD and SKCM, and narrowly distributed in UVM and mesothelioma (MESO), which may be attributed to the fact that some cancer types had more than one subtype and therefore more genetic diversity." (PMID 35910024, 2022).
mucinous ovarian tumors (3 papers, 2015 to 2024). "From these reports, it appears that loss of Cdkn2a in mucinous ovarian tumors with V600E BRAF mutation impairs progression to carcinoma." (PMID 32556513, 2020). "BRAF and KRAS mutations are components of the mitogen-activated protein kinase (MAPK) cascade and KRAS mutations are common in mucinous ovarian tumors and prevalent among 40–50% of MOC cases." (PMID 32556513, 2020).
oral cancer (3 papers, 2019 to 2020). "One of the tumor samples examined was an “M” class tumor with a high confidence BRAF:p.G469A:c.1406G>C somatic mutation, which is the first to be reported in oral cancer." (PMID 32426287, 2020). "Tumor 2 showed a high confidence BRAF:p.G469A:c.1406G>C somatic mutation (classified as “M” class tumor), which is the first to be reported in oral cancer." (PMID 32426287, 2020). "Some of these genes, including AKT, BRAF, PIK3CA, NRAS, GSK3, CNND1, etc., are involved not only in oral cancers but, generally, in several solid tumors." (PMID 31052345, 2019). "In the oral cancer cells (HSC4, OSC19) that were used in this study, high expression of EGFR was confirmed, but no mutations of BRAF, HRAS, KRAS, and NRAS were observed." (PMID 32878053, 2020).
pericardial effusion (3 papers, 2020 to 2025). Fluid collection within the pericardial sac, usually due to inflammation. "BRAF mutations have been described in a case characterized by CNS involvement with histologic evidence of emperipolesis recognized as ECD/RDD overlap disease, as well as in a case presenting with multiple bone lesions and pericardial effusion reported as ECD with emperipolesis." (PMID 39592527, 2024).
perineurioma (3 papers, 2018 to 2025). A usually benign perineurioma not associated with a nerve, arising from the soft tissues. "In cases of usual perineuriomas, stromal cell proliferation is suggested to be a concern for serrated crypts that often harbor BRAF mutation." (PMID 40091909, 2025). "The current case is the first reported colorectal perineurioma where the BRAF V600E mutated protein was demonstrated by immunohistochemical detection." (PMID 29463272, 2018). "Alternatively, in the BRAF-positive serrated types of perineuriomas, surveillance is equivalent to intervals designated to serrated polyps due to a similar malignant potential." (PMID 31404377, 2019).
plasma cell disorders (3 papers, 2017 to 2023). "Despite the low incidence of BRAF mutations in these entities, Andrulis found 2.8% BRAF V600E cases out of the 379 patients with plasma cell disorders." (PMID 27738305, 2017). "From a cohort of 217 patients with plasma cell neoplasm that underwent NGS mutation profiling, we identified 68 (31.3%) patients who had mutations in RAS signaling pathway genes (KRAS, NRAS or BRAF) and no other mutations." (PMID 37212518, 2023).
plasma cell leukemia (3 papers, 2017 to 2023). An aggressive plasma cell neoplasm characterized by the presence of neoplastic plasma cells in the peripheral blood. "According to published data, mutations of RAS family genes (KRAS, NRAS, BRAF) occur in less than 10% in MGUS, in 50% of symptomatic MM, and in more than 70% of cases of plasma-cell leukemia, which indicates activation of this pathway in the progression of the disease." (PMID 36833278, 2023). "Hence, other attempts were made to determine whether BRAF mutations are present in multiple myeloma (MM) and plasma cell leukemia (PCL)." (PMID 27738305, 2017).
pneumonitis (3 papers, 2015 to 2024). An inflammatory process affecting the lung parenchyma. "We report for the first time two sequential episodes of pneumonitis presumably induced by trametinib (a MEK inhibitor) and vemurafenib (a BRAF inhibitor) in a 50 year-old man." (PMID 26481107, 2015).
radiation dermatitis (3 papers, 2016 to 2024). "In patients receiving concurrent BRAF inhibitor with whole brain radiotherapy, the incidence of radiodermatitis was significantly greater in patients receiving combined therapy: reported as 44% for combination compared to 8% receiving radiation alone." (PMID 34277419, 2021). "An increased rate and severity of radiation dermatitis has been observed when BRAF inhibition is used concomitantly with conventionally fractionated radiotherapy." (PMID 27200295, 2016). "We hypothesize that the paradoxical activity of a BRAF inhibitor could be leveraged in the setting of acute radiation dermatitis, where temporary hyperproliferation is desirable to repopulate the epidermal keratinocytes and restore the skin barrier." (PMID 38405632, 2024). "Thus, it remains to be understood if rates of radiodermatitis with BRAF inhibitor plus radiation are improved with addition of MEK inhibitor." (PMID 34277419, 2021).
reactive disorder (3 papers, 2015 to 2025). "LCH is considered a reactive disorder with a potential underlying neoplastic component, resulting from chronic inflammatory processes exacerbated by the BRAF mutation." (PMID 39958088, 2025). "LCH may be a reactive disorder with both underlying neoplastic potential of antigen presenting cells harboring BRAF mutations and hyper-immunity of other inflammatory cells against MCPyV infection." (PMID 26097443, 2015). "Recent studies have shown that approximately one-third of patients with RDD harbor mutations in genes involved in the MAPK/ERK pathway, such as NRAS, KRAS, MAP2K1, and, rarely, BRAF, indicating a neoplastic process rather than a reactive disorder." (PMID 40385897, 2025).
salivary gland tumor (3 papers, 2015 to 2025). "While pleomorphic adenoma and metanephric adenofibroma can be differentiated based on a history of prior salivary gland tumor, metanephric adenofibroma is associated with strong nuclear immunoreactivity for WT1 and BRAF V600E in the epithelial component." (PMID 41268216, 2025).
sarcomatoid carcinoma (3 papers, 2015 to 2025). A malignant epithelial neoplasm characterized by the presence of spindle cells and anaplastic morphologic features. "Eight sarcomatoid carcinoma were analyzed for the presence of EGFR kinase domain mutations, KRAS mutations, HER2 kinase domain mutations, BRAF mutations, ALK fusions, RET fusions and AKT1 mutations." (PMID 26486077, 2015). "Moreover, other new mutations in sarcomatoid carcinoma, such as integrin cell surface interactions, WNT, MAPK, and BRAF signaling pathways, induce EMT phenotypes." (PMID 40231252, 2025). "BRAF mutations may also occur in only adenocarcinomas; thus, BRAF inhibitors may not appreciably affect spindle cell carcinomas." (PMID 40104449, 2025).
Sepsis (3 papers, 2022 to 2025). Sepsis is defined as life-threatening organ dysfunction caused by a dysregulated host response to infection. "Patient 26 (PCP with BRAF V600E mutation) received a therapy with dabrafenib/trametinib, which was discontinued after three months despite a partial response on MRI because of sepsis-like episodes." (PMID 35864412, 2022). "Two patients discontinued treatment due to side effects: In patient 26 (PCP with BRAF V600E mutation) therapy with dabrafenib/trametinib was discontinued after three months despite a partial response on MRI because of three episodes of fever, some of which were sepsis-like (CTCAE grade 4)." (PMID 35864412, 2022).
serrated polyposis (3 papers, 2011 to 2021). "The balance of CRC (BRAF wild-type) in serrated polyposis either demonstrates somatic KRAS mutation at a rate of approximately 19% which is half that of the population or is oncogene mutation null." (PMID 21660283, 2011). "CRCs in serrated polyposis have shown somatic BRAF mutation in 33% of 6 cases in an early published report and, consistently, in 19/58 (33%) of a recent case series." (PMID 21660283, 2011). "If most of the CRCs in serrated polyposis were to arise from advanced serrated polyps, a high rate of BRAF-mutated CRC would be expected." (PMID 21660283, 2011). "When multiple lesions are examined, serrated pathway features of BRAF mutation and CIMP demonstrate a high rate of concordance between discrete lesions in individuals with serrated polyposis." (PMID 21660283, 2011). "Given that the major association between smoking and CRC is largely confined to those CRCs with somatic BRAF mutation, and less than one-third of CRCs in serrated polyposis harbor a BRAF mutation, this is perhaps not unexpected, as BRAF-mutated CRCs constitute a minority of serrated polyposis CRCs." (PMID 21660283, 2011).
skin papilloma (3 papers, 2017 to 2024). A benign papillary neoplastic growth on the skin composed of epithelial cells and a fibrous stalk. "3.37% of patients from the BRAF and MEK inhibitor treatment group had a decrease in skin papilloma compared with 18.47% in BRAF inhibitor alone group." (PMID 39776585, 2024). "In a two-stage skin carcinogenesis mouse model, the skin papillomas induced by 7,12-dimethylbenz[a]anthracene (DMBA)/12-O-tetradecanoylphorbol-13-acetate (TPA) (DT) resemble the lesions in BRAF inhibitor-treated patients." (PMID 31242703, 2019).
Squamous Cell Anal Carcinoma (3 papers, 2014 to 2022). "Epidermal growth factor receptor (EGFR) is usually expressed in squamous cell anal carcinoma (SCAC) and anti-EGFR agents could represent a valid treatment strategy, also considering that KRAS and BRAF mutations are rare events in this type of cancer." (PMID 27886225, 2016). "Moreover, cetuximab may be an effective treatment for anal squamous cell carcinoma because EGFR is overexpressed in many cases, while KRAS, NRAS, and BRAF mutations are not observed in most cases." (PMID 35723765, 2022).
syringocystadenoma papilliferum (3 papers, 2021 to 2025). A benign adnexal neoplasm occurring during childhood or adolescence. "Notably, syringocystadenoma papilliferum of the skin, histologically analogous to SP, also exists BRAF and HRAS mutations, which suggests SP may be considered to be a salivary counterpart of syringocystadenoma papilliferum of the skin." (PMID 33712056, 2021). "Recently, the genetic mutations of BRAF and HRAS have been reported in SP, considering it to be the salivary complement of benign sweat tumor of skin, syringocystadenoma papilliferum." (PMID 41322839, 2025).
undifferentiated sarcoma (3 papers, 2024 to 2025). "The prevalence of BRAF-mutated cases among soft-tissue neoplasms is tumor-specific, estimated as high as 15–20% for malignant peripheral nerve sheath tumors and as low as 0.5–9% for undifferentiated sarcomas." (PMID 39018206, 2024). "A previously undetected BRAF p.V600E mutation was emblematic of the clinical utility of this approach in a patient with a liver undifferentiated embryonal sarcoma responsive to BRAF/MEK inhibition." (PMID 38750555, 2024). "The current case of undifferentiated sarcoma in adolescent was diagnostically challenging as its BRAF V600E-positive mutation status was not accompanied by corresponding immunopositivity." (PMID 39018206, 2024). "A documented case of BRAF V600E-mutated undifferentiated sarcoma demonstrated successful treatment with a combination of BRAF and MEK inhibitors, suggesting that the BRAF V600E mutation could be a viable therapeutic target when addressed with dual BRAF and MEK inhibition." (PMID 40909947, 2025).
uveal tumours (3 papers, 2003 to 2012). "Similarly, our observation of a complete lack of BRAF mutations in primary uveal tumours mirrors the findings of several recent reports." (PMID 15928660, 2005).
vascular malformation (3 papers, 2019 to 2022). A non-neoplastic disorder that is the result of defects of vascular morphogenesis. "The specific mutations of MAP2K1(K57N), MAP2K1(Q58del) and BRAF(V600E) show strong activation on ERK, which may account for significant activation of the MAPK pathway in those sporadic vascular malformations." (PMID 31067686, 2019). "In addition to sclerotherapy and surgical excision, protein inhibitors involved in the signaling pathways PI3K/AKT/mTOR or RAS/BRAF/MAPK/ERK appear as targeted therapeutic options for different types of vascular malformations, so far, the clinical results being promising." (PMID 36293054, 2022).